PALB2 (partner and localizer of BRCA2)
Diseases named in the same sentence as PALB2 in open-access papers (continued):
Sharing a sentence is not in itself a finding about the gene and the disease.
tumor (continued). "TNBC versus other tumor subtype was significantly more frequent among AA patients with pathogenic variants in BRCA2 or PALB2 than among AA cases with no such variants (OR = 2.95 [1.18, 7.37])." (PMID 33479248, 2021). "Although defects in other key HRR proteins such as PALB2 account for some of these HRD-positive tumours, it is also important to highlight that some HRR genes, in particular BRCA1 and RAD51C, show high levels of promoter hypermethylation leading to gene silencing in breast and ovarian cancer." (PMID 35008208, 2021). "Another HRR-related gene, PALB2, was altered in a single tumour." (PMID 34680387, 2021). "Loss of heterozygosity (LOH) analysis was performed on DNA from both tumours to support the role of the SDHA variant being causal and also investigate whether there was any evidence for the PALB2 variant contributing to tumourigenesis." (PMID 33854214, 2021). "In contrast, 5 patients with BRCA1, BRCA2, and PALB2—all found in patients with tumor types not known to be associated with GPVs in these genes—did not have second hit and are unlikely to respond to PARP inhibitors." (PMID 34792595, 2021). "Nine cases with germline variants in HR-related genes PALB2, BRCA1, RAD51C, FAN1 and CHEK2 also showed evidence of enrichment of the germline variant in the tumor, while the other 12 cases with HR-related gene variants (seven FAN1, three CHEK2, one BRIP1, one NBN) did not." (PMID 33917078, 2021). "PALB2 functions as a tumor suppressor and participates in the maintenance of genome integrity." (PMID 32185139, 2020). "Deletion patterns can most accurately identify defects of BRCA2 and PALB2, also confirmed in tumor genomes; therefore, a high proportion of deletions with microhomologies may be a good predictor of treatment with PARP inhibitors, cisplatin or carboplatin." (PMID 31727117, 2019). "PALB2 is often described as the hub for a network of tumor suppressors." (PMID 31017574, 2019). "As dysfunction of BRCA1 and BRCA2 promotes carcinogenesis through promoting genomic instability 16, PALB2 has been hypothesized to be a tumor suppressor gene." (PMID 29321957, 2018). "The mRNA levels of CDK12, PALB2 and XPF inversely associated with the in vivo DDP antitumor activity; higher CDK12 mRNA levels were associated with a higher recurrence rate in ovarian patients with low residual tumor." (PMID 29872499, 2018). "Similarly, a patient with a PDAC tumour harbouring biallelic inactivation of the PALB2 gene, had an exceptional response to mitomycin C." (PMID 30428574, 2018). "Four variants [c.1393G>C (p.Gly465Arg) and c.2179G>A (p.Gly727Arg) in GLI3, c.360C>T (p.Ala120=) in CDKN2B and c.2794G>A (p.Val932Met) in PALB2] were identified in tumours that developed recurrence and in all cases were present both in primary and recurrent samples." (PMID 30344923, 2018). "The rs420259 is located in an intron of PALB2 gene which is involved in tumor suppression." (PMID 28283021, 2017). "Therefore, the integrity of these protein domains is essential for the maintenance of PALB2 tumor suppression function." (PMID 28858227, 2017). "The decrease in survival and increase in tumor predisposition of Brca2G25R mutant mice on Palb2Ko/+ genetic background provides strong evidence to suggest that normal levels of interaction between BRCA2 and PALB2 is essential for tumor suppression." (PMID 27490902, 2016). "The Brca2G25R/Ko;Palb2Ko/+ animals that result in the least interaction between BRCA2 and PALB2 and exhibited the shortest tumor latency, predominantly developed lymphoblastic T-cell lymphomas, similar to the mice carrying a truncating mutation in exon 11 of Brca2." (PMID 27490902, 2016). "Our results indicated that germline truncation and missense variants in several genes were under selection in the tumour, with ATM, BRCA1, BRCA2 and RAD51C determined as significant from both truncation and missense analyses and BAP1, BRIP1, FANCM, PALB2 and RAD51D from truncation analysis alone." (PMID 26689913, 2015).
tumor (continued). "Therefore, it can be concluded that WTX and PALB2-mediated tumor suppression can be ascribed, at least in part, to maintaining an increased cellular Nrf2 level." (PMID 25014534, 2014). "In particular, WTX and PALB2 are considered as bona fide tumor suppressors." (PMID 25014534, 2014). "This supports the proposal that PALB2 is important for BRCA2 tumor suppression activity." (PMID 23935836, 2013). "Despite the fact that CTCs are difficult to be unquestionably identified as tumor cells, they are frequently associated with invasiveness and treatment resistance, and in our analysis an EMT CTC overexpressed DNA repair genes, consistent with platinum sensitivity and BRCA2/PALB2 status." (PMID 41367869, 2025). "Samples from the PALB2-mutated case P-T2 showed staining for IQGAP1 at medium intensity in cytosol, becoming high-intensity in the periphery and in the plasma membrane; CK7-specific staining was at saturation level in the cytosol of tumor cells, leaving a noticeable intercell space." (PMID 40868059, 2025). "As PALB2 truncation impairs homologous recombination repair and promotes genomic instability, downstream effects on cytoskeletal regulation may enhance the motile and invasive phenotype of tumor cells through some mechanisms other than IQGAP1." (PMID 40868059, 2025). "Due to the young age of this PALB2 P/LP variant carrier, PALB2-related tumor types could not be excluded in the future." (PMID 37686625, 2023). "Based on clinical germline or tumor testing performed prior to enrollment, 19 patients had a germline BRCA1 (n = 6) or BRCA2 (n = 13) mutation, and 1 had a germline PALB2 mutation; 2 patients had a BRCA2 variant of uncertain significance (VUS) and 1 patient had a PALB2 VUS." (PMID 35750695, 2022). "The number and locations of tumors, quadrant of tumors, regularity of tumor margins, presence of blood flow signals, presence of posterior echo attenuation, presence of calcification, histological grade, molecular typing, and mutations of BRAF, ATM, and PALB2 were irrelevant factors (P > 0.05)." (PMID 35255911, 2022). "Given that familial wtGIST is rare, we performed further tumour studies to investigate whether there was evidence for the PALB2 variant contributing to increased penetrance as opposed to being an incidental finding." (PMID 33854214, 2021). "We also include an analysis of the genomic and transcriptomic landscape of the DDR PARP genes and key HR genes (BRCA1, BRCA2, ATM, RAD51, MRE11, PALB2) in GI patient tumours (n = 1744) using publicly available datasets to identify patients that may benefit from PARPi therapeutic approaches." (PMID 34440228, 2021). "BRCA1 methylated tumours are also sensitive to PARP inhibition, as are tumours with mutations in other genes that function in repair of double strand breaks (DSBs), including RAD51C, RAD51D, ATM and PALB2, where tumours are described as having a “BRCAness” phenotype." (PMID 34445211, 2021). "The evidence that PALB2 is critical for HR and functions as a breast and pancreatic susceptibility gene suggest that the role of the adaptor protein, PALB2, may be critical for BRCA1/2- mediated tumor suppression by physically linking BRCA1 to BRCA2." (PMID 31877165, 2019). "Thus, we hypothesized that the role of the PALB2 linker protein may be critical for BRCA1/2-mediated tumor suppression." (PMID 31877165, 2019). "Hence, to circumvent the embryonic lethality and to study the role of these tumor suppressors in pancreatic development and malignant transformation, we specifically deleted Palb2, Brca1 or Brca2 in the pancreas only using the Cre-LoxP recombination technology." (PMID 31877165, 2019).
tumor (continued). "While the PALB2 expression-cutoff for haplosufficiency is unknown, we previously showed that variants expressing ≥ 30% of the ATM full-length transcript cannot be classified as pathogenic or, in other words, these variants would keep their tumor-suppressor activity." (PMID 39518003, 2024). "Partner and localizer of BRCA2, FANCN (PALB2), like CHEK2, acts as a tumor suppressor, takes part in the repair of damaged DNA and promotes the expression of antioxidant genes." (PMID 38785550, 2024). "Tumor sequencing revealed LOH in CHEK2 and PALB2, as well as CCND1,FGFR1, GPR124, ZNF217, ZNF703, and PTPN1 amplifications." (PMID 38091153, 2024). "Remarkably, Palb2f/f;Atg7f/f;Wap-Cre (Palb2;Atg7-CKO) mice exhibited greatly reduced overall survival (T50 = 280 days), even though their tumor development was also greatly reduced." (PMID 35404932, 2022). "In our cohort, a comprehensive tumor profile including homologous recombination genes (i.e., ATM, PALB2, RAD50, RAD51, RAD51B, RAD51C, RAD51D...) was performed for 100 cases, finding pathogenic alterations in four tumor samples, as previously reported." (PMID 35406410, 2022). "This is critical in determining one‐copy vs. total deletion or LOH in actionable tumor suppressor such as BRCA1, BRCA2, and PALB2, which are targetable only when inactivated biallelically." (PMID 34866317, 2022). "This is especially imperative in determining one‐copy vs. total deletion or LOH of actionable tumor suppressors such as BRCA1, BRCA2, PALB2, and others for which biallelic inactivation would make them eligible for targeted therapy." (PMID 34866317, 2022). "Tumor analysis highlighted germline variation in HR-related repair genes, particularly BRCA1, PALB2 and RAD51C, to have a potential driver role in EC development based on the presence of mutational signature indicative of HR deficiency." (PMID 33917078, 2021). "Deleterious alterations in DDR genes associated with increased sensitivity to PARP inhibitors in other tumor types (e.g. BRCA1, BRCA2, PALB2, RAD51C and RAD51D) were infrequent (9.4%) in ATLAS." (PMID 34030643, 2021). "To determine the level of tumor-infiltrating immune cells, we examined CD3+ T cells and F4/80+ macrophages in tumors from KPC, Palb2-KPC, Brca1-KPC, and Brca2-KPC animals." (PMID 31877165, 2019). "The PALB2 and BRCA2 proteins are capable of helping the regulation of the cell growth, and division of cell, as well as are as tumor suppressors." (PMID 30975222, 2019). "PALB2 mediates interactions between BRCA1 and BRCA2 proteins, acts as a scaffold connecting numerous tumor suppressors, stimulates Polη-dependent DNA synthesis and RAD51 recombinase activity." (PMID 27434671, 2016). "The other Keap1 binding proteins, such as the Wilms tumor gene on the X chromosome (WTX), PALB2/FANCN, and dipeptidyl peptidase 3 (DPP3) also contain the ETGE motif in common and can promote the Nrf2 protein stability by competitively binding to Keap1." (PMID 25014534, 2014). "As in the targeted monotherapies, also in the combinatorial setting, routine multi-gene NGS of both tissue and circulating tumor DNA is now the standard of care, with the 2025 NCCN guideline mandating HRR-gene screening (BRCA1/2, ATM, PALB2, etc.)for every mCRPC patient." (PMID 40806607, 2025). "PALB2 showed outlier high expression (99th percentile) as did other genes involved in HR including BRCA1 (94th percentile), BRCA2 (100th percentile), and HERC2 (100th percentile) in this tumor." (PMID 38755180, 2024). "Panel sequencing of HRR-related genes additionally identified 1 tumor with a likely BRCA1 PV with gsLOH, 2 with BRCA2 PVs with gsLOH, and 1 tumor with a PV in PALB2 without gsLOH." (PMID 38648056, 2024).
tumor (continued). "BRCA1, BRCA2, ATM, PALB2, and BAP1 were the DNA damage response GA found in our tumor samples." (PMID 36831055, 2023). "As recently reported, an NGS profiling including HR genes (BARD1, BRIP1, PALB2, RAD51C, and RAD51D) could improve the rate of tumor with HRD by 5–6%, identifying patients who may mostly benefit from PARPi therapy." (PMID 35406410, 2022). "The mechanism for a stronger association of a diagnosis of TNBC versus other tumor subtypes with BRCA2 and PALB2 among patients of African and AA ancestry is not obvious." (PMID 33479248, 2021). "Whilst the role of PALB2 and ATM is fairly well established in PC, RAD50 is not among the genes generally associated with this tumour." (PMID 34034685, 2021). "Therefore, BRCA2 is a classic tumor suppressor gene, similar to related tumor suppressors such as BRCA1 and PALB2, which also function in the cellular response to DNA damage and in the maintenance of genetic/genomic stability." (PMID 34356050, 2021). "Moreover, we confirmed the mutation in ARID1A gene (p.R1276∗), ERBB3 (p.S128R), KEAP1 (p.R135H), PALB2 (p.P807S), and NTRK1 (p.Q736X), previously reported by F1CDx, both in the tumor and in the ccfDNAs." (PMID 34178989, 2021). "In contrast, the relationship between a diagnosis of TNBC versus any other tumor subtype and BRCA2 and PALB2 might be different for AA and EA patients." (PMID 33479248, 2021). "As PALB2 exhibits functions in the BRCA1/2-RAD51-dependent homologous DNA recombination repair pathway, we sought to use ex vivo functional screening to explore sensitivity of the tumor cells to therapeutic targeting of DNA repair." (PMID 34084283, 2021). "Her ERBB2-overexpressing tumor did not however present a somatic second hit affecting PALB2, nor have a high HRD score." (PMID 32295625, 2020). "The VUS in the gene PALB2 c.1001A>G, identified in ID85, showed LOH in the tumor." (PMID 33134171, 2020). "Interestingly, Palb2-KPC tumors showed a mixture of Brca1-KPC and Brca2-KPC tumor phenotypes regarding the presence of cysts." (PMID 31877165, 2019). "The mixed phenotype of Palb2-KPC tumors could be due to the role of PALB2, as a linker protein between BRCA1 and BRCA2, in BRCA1/2 mediated tumor suppression." (PMID 31877165, 2019). "Higher PALB2 expression level was detected in patients with higher tumor histological grade (II–III and III) or with Her‐2 negative status." (PMID 29321957, 2018). "PALB2 showed a more uniform distribution without obvious tumor-specific enrichment." (PMID 41602397, 2026). "Similarly to BRCA2, a case with germline PALB2 mutation and the absence of somatic LOH had a chromosomally stable tumor." (PMID 41465280, 2025). "Mutational signature analyses showed the pooled somatic variants from the LLGL2-inactivated tumours were more like the ATM-inactivated tumours as opposed to the PALB2-inactivated tumours, with GEL-Ovary_common_SBS5 and GEL-Ovary_common_SBS1+18 signatures prominent." (PMID 39794353, 2025). "Our findings suggest a functional link between PALB2 protein and alterations in IQGAP1 expression and subcellular localization which may contribute to tumor progression through the deregulation of cellular proliferation, migration, and cytoskeletal organization." (PMID 40868059, 2025). "However, the differences in the distribution of the tumor Immunohistochemical characteristics between PALB2 carriers and non-carriers were not statistically significant." (PMID 38914840, 2024).
tumor (continued). "The somatic NAHR burden did not vary by tumor type nor was it lower in tumors harboring biallelic pathogenic mutations in DNA repair genes, including frequently mutated homologous recombination pathway mediators (BRCA1, BRCA2, PALB2 and RAD51C)." (PMID 37945902, 2023). "However, in the HRD tumor population analysed in this study, no germline alteration in PALB2 was observed." (PMID 32719318, 2020). "To examine the relevance of physical interaction between BRCA2 and PALB2 on the tumor suppressor function of BRCA2, we generated a cohort of control (wild-type and Brca2Ko/+), Brca2G25R/+, Brca2G25R/G25R, and Brca2G25R/Ko animals and monitored their tumor free survival for 2 yrs." (PMID 27490902, 2016). "Among 4 analyzed PALB2-associated PCs, all three cases with germline alterations accompanied by somatic LOH of the wild-type allele had HRD score higher or very close to the chosen threshold, and the case with germline mutation without LOH had chromosomally stable tumor (score = 0)." (PMID 41465280, 2025). "Based on this evidence, one could propose that because RAD51 possesses both BRCA1/2/PALB2-dependent and BRCA1/2/PALB2-independent functions during replication, its inactivation would be more toxic than that of one of the loading factors, thus impairing the proliferation of tumour cells." (PMID 34316706, 2021). "This is exemplified by PARPi used to treat breast, prostate, pancreatic or ovarian cancers with defects in the HR pathway, controlled by the tumour suppressors including (but not exclusive to) BRCA1, BRCA2, PALB2, RAD51C and RAD51D." (PMID 35567571, 2022). "However, the underlying mechanism is likely more complex, and the delayed tumor formation could also be due to a non-HR DNA repair defect, a DNA replication defect or other defects that lead to cell death or senescence upon combined loss of BRCA1 and PALB2." (PMID 33893322, 2021). "PALB2 and RBM10 are involved in DNA repair; their involvement in the tumor process is not surprising." (PMID 34284772, 2021). "Subsequent RNA-seq and western blot revealed that the expression of HIF1ɑ was closely correlated with HIF1A duplication in tumor tissues, whereas gene expression of CDKN2A and PALB2 was not significantly changed (fold-change < 2)." (PMID 30062063, 2018). "Interestingly, as seen in the merging, in some tumor cells of the control case, the expression intensity of IQGAP1 (yellow arrowheads) is prevalent over CK7 (15 ± 3.0%) and never in the truncated PALB2 case." (PMID 40868059, 2025). "The absence of tumor cells with predominant IQGAP1 expression over CK7 in the mutant background further underscores a possible deregulation of IQGAP1 compartmentalization and function upon PALB2 truncation." (PMID 40868059, 2025).
genetic disorder (3 papers, 2010 to 2024). "FA syndrome is a genetic disorder caused by germline biallelic mutations in one of 13 genes (including FANCD1/BRCA2 and FANCN/PALB2) of the so-called FA/BRCA pathway; this pathway controls the repair of double strand-breaks and the response to DNA crosslinking agents." (PMID 20122277, 2010).